ORM1 (orosomucoid 1)
Diseases named in the same sentence as ORM1 in open-access papers (continued):
Sharing a sentence is not in itself a finding about the gene and the disease.
tumor (31 papers, 2009 to 2025). "ORM1 has been implicated in both anti-apoptotic and proangiogenic processes across various cancers, suggesting its potential role in tumor progression." (PMID 40299486, 2025). "ORM1 is linked to tumor immunity, including antigen processing and presentation, T-cell receptor signaling, and cytokine-cytokine receptor interactions." (PMID 36998443, 2023). "In this study, we found that ORM1 is differentially expressed between tumor and non-tumor tissues and was associated with tumor growth, drug sensitivity, and microvascular invasion (MVI)." (PMID 35765957, 2022). "Orosomucoid-1 was widely expressed in each tumor variant analyzed in this study, and differential orosomucoid-1 expression was observed between benign and malignant tumor." (PMID 27386438, 2016). "Conversely, with cRaf transgenic animals, orosomucoid 1 (Orm1) is the only immune response gene that is upregulated (threefold) and a recent study demonstrated Orm1 to enhance the immunosuppressive function of tumor-associated macrophages (TAMs)." (PMID 38245882, 2024). "Indeed, ORM1 has been reported to be associated with prognosis or progression of tumor." (PMID 37735575, 2023). "Hence, we hypothesized that ORM1 may promote CRLM in part by regulating macrophage M2 polarization which contributes to the secretion of associated pro-tumor cytokines." (PMID 37640741, 2023). "Many biomarkers can be detected in blood circulation: circulating tumor cells, circulating tumor DNA/RNA (ctDNA/ctRNA), miRNA, exosomes, and bodily secretions like ORM1, calprotectin and M2 pyruvate kinase)." (PMID 37599857, 2023). "Specifically, ORM1 potentially acts as an inhibitory factor to protect tumor cells from attack by the immune system, thereby leading to the immune escape of tumors." (PMID 36998443, 2023). "Based on the data from the TCGA database, we displayed that the protein expression level of ORM1 in primary tumor tissues (n = 110) was significantly stronger than the normal tissues (n = 84)." (PMID 37735575, 2023). "In contrast, the methylation level of ORM1 promoter was much lower in primary tumor tissues (n = 324) than the normal tissues (n = 160)." (PMID 37735575, 2023). "The results of these assays were in accordance with our bioinformatics analysis, which suggested that ORM1 expression was upregulated in the cancer embolus compared to that in the surrounding tumor cells." (PMID 35765957, 2022). "As expected, the results revealed that ORM1 and PTHLH were associated with tumor immunity, such as antigen processing and presentation, T cell receptor signaling pathway and cytokine-cytokine receptor interactions." (PMID 33391264, 2020). "Consistent with previous studies, we found that tumor burden resulted in elevated hepatic Il1b, Ifna, Lcn2, Apcs, Crp, and Orm1." (PMID 31615993, 2019). "We now consider this possibility because the particular characteristics of this tumor type such as growth and vascularization are consistent with those seen in other tumors in which ORM1 has been found." (PMID 27386438, 2016). "Differences in ORM1 expression revealed that AC expressed ORM1 in more sites within neoplasms and that ORM1 is more abundant in AC than in SMAs and UAs." (PMID 27386438, 2016). "To determine the in situ ORM1 expression pattern in clinically obtained tumor samples, we performed immunohistochemical assays using a monoclonal ORM1 antibody." (PMID 27386438, 2016). "The high expression of ORM1 can act as a defense mechanism against tumor cell proliferation and invasion." (PMID 27386438, 2016). "To identify ORM1 protein in tumor samples, we performed Western blot assays using a commercial monoclonal antibody." (PMID 27386438, 2016). "Human liver cells are normally the site of ORM1 production, but it can also be produced in endothelial cells and some tumor cells." (PMID 25215505, 2014). "Human hepatocytes are normally the site of ORM1 production, but endothelial cells and some tumor cells can also produce it." (PMID 22888844, 2012).
tumor (continued). "A spot consistently overexpressed in odontogenic myxoma was identified as the orosomucoid 1 protein, which was located in the cytoplasm of the tumor cells." (PMID 22888844, 2012). "Moreover, MC38 cells overexpressing ORM1 enhanced the tumor immune microenvironment by promoting macrophage M2 polarization and elevating interleukin-10 (IL-10) expression." (PMID 37640741, 2023). "Similarly, based on our results, ORM1 was validated to be acting as both a tumor suppressor and a tumor promoter in HCC." (PMID 35765957, 2022). "However, three classical acute phase reactants, Apcs, Orm1, and Crp, were significantly decreased in tumor-bearing animals treated with R848 compared with vehicle, consistent with decreased tumor burden-associated inflammatory responses." (PMID 31615993, 2019). "For example, although ORM1 expression was found in the analyzed samples, whether ORM1 expression was induced or merely increased in response to tumor growth or the onset of neoplastic cell production remains unknown." (PMID 27386438, 2016). "Alternatively, given its anti-inflammatory activity, ORM1 overexpression could inhibit the immune response, resulting in increased tumor cell proliferation." (PMID 27386438, 2016). "The presence of ORM1 in OM possibly can justify the classical mucoid appearance of this tumor." (PMID 22888844, 2012). "Notably, Cldn2, Fetub, Fst, Orm1, S100a14 and RasGRF1 were primarily detected in the cytoplasm of bronchial normal cells and tumor cells." (PMID 19812696, 2009). "Furthermore, in vascular invasion specimens, ORM1 expression was higher in the cancer embolus than in the surrounding tumor cells, suggesting that ORM1 expression may be related to vascular invasion, thereby reducing the overall prognosis of HCC patients." (PMID 35765957, 2022). "Additionally, the acidity and other properties of ORM1 may contribute to tissue degradation, thereby easing tumor growth." (PMID 27386438, 2016). "ORM1 might play a role in defense or resistance mechanisms against tumor cells specifically by reducing the proliferation, invasion, and metastasis of cancer cells, thereby influencing tumor invasion and growth." (PMID 27386438, 2016). "Thus, the overexpression of ORM1 in OM may inhibit the immune response, resulting in an increase of tumor cell proliferation." (PMID 22888844, 2012). "However, it is uncertain whether the serum levels of acute-phase proteins, such as ORM1, increase as a response of the host to tumor growth or as a consequence of neoplastic cell production." (PMID 22888844, 2012). "Orosomucoid 1 (ORM1) is one of the most well-characterized acute phase proteins that have been associated with many cellular pathways, including immunity, tissue regeneration, metabolism, and cancer development which may help tumor cells prevent cellular decay as a result of the adverse environment." (PMID 35765957, 2022). "The expression of ORM1, an acute-phase protein, was significantly downregulated in HCC tissues in both GSE45114 and GSE45267 compared to that of adjacent non-tumor tissues." (PMID 35765957, 2022). "Using a combination of in vitro, in silico, and immunohistochemistry in clinical samples, we were able to show that ORM1 was differentially expressed in HCC tumor and non-tumor tissues, which was in accordance with the findings of previous studies." (PMID 35765957, 2022). "Although ORM1 was downregulated in HCC tissues, it was positively correlated with microvascular invasion and promoted tumor growth and drug resistance." (PMID 35765957, 2022). "In addition, acute phase proteins (ORM1, CRP, SAA1) and complement cascade components (SERPINA1, C5, FGA) showed an obviously significant correlation with tumor size, reflecting a positive connection between inflammatory response and tumor size." (PMID 37460463, 2023).
tumor (continued). "The detectable tumor numbers in the LM of mice treated with MC38/ORM1 cells (LM/ORM1) were higher than those in mice treated with MC38/NC cells (LM/NC);, indicating that upregulation of ORM1 was effective in promoting CRLM." (PMID 37640741, 2023). "Considered together, ORM1 promotes CRC progression and liver metastasis by regulating tumor cell growth and inducing macrophage M2 polarization, which mediates tumor immune tolerance, and thus acts as a potential predictive marker and therapeutic target in CRLM." (PMID 37640741, 2023). "An in vitro assay also revealed that downregulation of ORM1 led to the suppression of tumor growth and enhancement of sorafenib sensitivity without epithelial-to-mesenchymal transition alteration, which was consistent with our bioinformatic analysis." (PMID 35765957, 2022). "The urine protein levels of LRG1 were higher in patients with AOSD than in patients with RA or neoplasms and HC subjects, and the urine protein levels of ORM1 and ORM2 in AOSD patients were dramatically higher than those in patients with RA, neoplasms, or infections and HC subjects." (PMID 33013889, 2020). "The properties and functions of ORM1 in this tumor are not clear, although the current evidence suggests possible immunomodulatory and/or angiogenic properties of this glycoprotein in the biological behavior of OM." (PMID 22888844, 2012). "Furthermore, ORM1 contributed to cell migration as well as invasion in KIRC, which suggests that ORM1 might be involved in the process of tumor metastasis." (PMID 37735575, 2023).
cancer (28 papers, 2009 to 2025). A tumor composed of atypical neoplastic, often pleomorphic cells that invade other tissues. "Current studies on ORM1 expression association with other cancers have focused on blood, urine and cancerous tissue and the level of salivary ORM1 expression in other cancer patients is worthy of further validation." (PMID 36096917, 2022). "Some studies have also demonstrated the diagnostic value of ORM1 in other cancers." (PMID 37640741, 2023). "ORM1 is an acute-phase protein whose levels increase rapidly under conditions of inflammation, stress, chronic diseases (cancer, etc.)and injury and can be modulated by glucocorticoids, TNF-α, IL-1, IL-8, IL-6, and IL-6-related cytokines." (PMID 37355563, 2023). "In our study, ORM1 was downregulated in cancer cells but upregulated in metastatic sites, with its primary expression focused on the cancer embolus." (PMID 35765957, 2022). "The expression of ORM1 is also altered in response to various health conditions, such as chronic inflammation, infection, injury, drug sensitivity, and cancer." (PMID 35765957, 2022). "The mRNA expression level of ORM1 was analyzed through integrative analysis of Gene Express Omnibus and The Cancer Genome Atlas datasets." (PMID 35765957, 2022). "ORM1 codes for orosomucoid 1, which is suggested to induce the conversion of monocytes to M2b macrophages in response to type 2 cytokines in cancer patients." (PMID 30577850, 2018). "Several studies in the literature have described the use of ORM1 in the diagnosis of different cancer types such as bladder, colorectal, or ovarian cancer." (PMID 27386438, 2016). "By contrast, recent studies have demonstrated that ORM1 may show a vital role as an oncogene in several cancers." (PMID 37640741, 2023). "Since ORM1 has already been validated as a marker of cancer transmission and MVI, we hypothesized that it is also a marker of overall survival." (PMID 35765957, 2022). "Based on these results, we hypothesized that ORM1 may be correlated with drug sensitivity, as all anti-cancer inhibitors induce cell stress, which must be overcome to facilitate chemoresistance." (PMID 35765957, 2022). "Although we validated the finding that ORM1 expression is downregulated in cancer cells and correlates with vascular invasion and drug sensitivity, we could not validate its negative influence on overall survival." (PMID 35765957, 2022). "Given the proposed immunosuppressive properties of ORM1, we hypothesize that an increase in ORM1 may allow cancer cells to escape immune surveillance, which warrants further study." (PMID 33808801, 2021). "Most cancer patients displayed increased levels of ORM1 in comparision with healthy controls." (PMID 27021626, 2016). "In addition to acting on cancer cells, ORM1 acts on the immune system." (PMID 37640741, 2023). "In addition, except for cancer cells, ORM1 was rich in stroma, which was also seen in our IHC results; thus, it may lead to different results in different studies." (PMID 35765957, 2022). "As ORM1 is related to cell growth, microvascular metastasis, and drug resistance, we explored whether it is associated with epithelial-to-mesenchymal transition (EMT), one of the most common processes in cancer." (PMID 35765957, 2022). "However, the expression levels of ORM1 vary among different cancers." (PMID 35765957, 2022). "In addition, elevation of ORM1 were discovered in certain cancer patients." (PMID 27021626, 2016). "Eight proteins (C-reactive protein, AGRN, XPOT, LDHA, C1QC, ORM1, ANGPTL4, and prostaglandin D2 synthase [PTGDS]) exhibited a continuously upward or downward trend in three or more cancer types." (PMID 39884577, 2025). "To further validate the difference between the expression levels of ORM1 in LM and PT of CRC, we collected 10 pairs of PT tissues and LM and their para-cancer (PC) tissues of CRC from the First Affiliated Hospital of Nanjing Medical University." (PMID 37640741, 2023).
cancer (continued). "Therefore, we hypothesize that ORM1 affects the sensitivity of epirubicin-resistant cancer cells." (PMID 34654351, 2021). "Several other acute-phase response proteins were also elevated towards diagnosis (e.g., HP, ORM1, ORM2, CRP, SERPINF2), presumably due to a host systemic inflammatory response—a known prognostic indicator in cancer patients." (PMID 29232830, 2017). "Orosomucoid 1 (ORM1), an essential immune system regulator in acute-phase reactions, might facilitate cancer cell immune evasion." (PMID 39749345, 2024). "In our study, ORM1 was downregulated in cancer tissues compared to adjacent normal tissues, but upregulated in cancer embolus." (PMID 35765957, 2022). "The expression of ORM1 and ORM2 is dysregulated in many malignant cancers." (PMID 34654351, 2021). "Upregulation of 48 proteins in samples of cancer patients was reported, that included several inflammation/acute phase-related proteins: A1AG1 (ORM1), A1AT (SERPINA1), AACT (SERPINA3), CO4B, CO9, HPT, ITIH4, LBP and SAA1, which upregulation was revealed also in our study." (PMID 26376850, 2015). "The five proteins that met our criteria for an increase in relative abundance in the cancer compared to the control were haptoglobin (HAPT), orosomucoid-1 (ORM1), leucine-rich alpha-2-glycoprotein-1 (LRG1), alpha-1 antichymotrypsin (AACT), and fibrinogen-alpha (FGA)." (PMID 20546617, 2010). "As the expression of glycoproteins is increased in many cancers, it was of no surprise that Orm1 was 11.1-fold overexpressed in dysplastic cells." (PMID 19529782, 2009).
infection (9 papers, 2012 to 2025). The state of being infected such as from the introduction of a foreign agent such as serum, vaccine, antigenic substance or organism. "Orosomucoid-1 (ORM1) is a heavily glycosylated molecule characteristically overexpressed during the acute phase response to stressor signals such as infection, injury and inflammation." (PMID 22916107, 2012). "In addition, we recently published the surprising finding that hepatic expression of pig ORM1 was significantly decreased at 24 hours after experimental infection with the pig lung pathogen Actinobacillus pleuropneumoniae serotype 5b." (PMID 23844161, 2013). "We previously reported a moderate but significant down-regulation of the pig AGP gene (ORM1) in liver tissue at 24 hours after experimental infection with Actinobacillus pleuropneumoniae serotype 5b, and this is now confirmed to be reflected in the circulating concentrations of pig AGP protein." (PMID 23844161, 2013). "Several genes such as CP, HP, and ORM1 are involved in the acute-phase response, indicating that a decrease in CEBPB can influence systemic responses to injury, infection, or other stress factors." (PMID 41002959, 2025). "Surprisingly, pig AGP was found to behave as a negative acute phase protein during a range of experimental infections and aseptic inflammation with significant decreases in serum concentration and in hepatic ORM1 expression during the acute phase response." (PMID 23844161, 2013).
inflammation (1 paper, 2024). Aberrant reaction of the microcirculation characterized by movement of fluid and leukocytes from the blood into extravascular tissues. "PRM results showed that Orm1 levels in the model group were 3.84 times higher than those in the control group, which indicated that carrageenan induced acute systemic inflammation in rats." (PMID 38396823, 2024).
ORM1 also shares sentences with these, for which no sentence is quoted: Stroke (4 papers); NK/T cell lymphoma (3); bacterial infections (2); cholangiocarcinoma (2); esophageal cancer (2); gout (2); head and neck squamous cell carcinoma (2); immune thrombocytopenia (2); laryngeal carcinoma (2); liver cirrhosis (2); lupus nephritis (2); melanoma (2); metabolic syndrome (2); pneumonia (2); rheumatoid arthritis (2); type 2 diabetes (2); Acute hepatitis (1); Alzheimer disease (1); Arthritis (1); autism spectrum disorder (1); autoimmune disease (1); Barrett esophagus (1); Behcet disease (1); bipolar disorder (1); bladder tumors (1); Blindness (1); bruxism (1); Cachexia (1); cardiomyopathy (1); Cerebral ischemia (1).
A further 51 diseases each share a sentence with ORM1 in 1 paper.